PLD1 (phospholipase D1)
Diseases named in the same sentence as PLD1 in open-access papers (continued):
Sharing a sentence is not in itself a finding about the gene and the disease.
Hepatic steatosis (2 papers, 2016 to 2021). Steatosis is a term used to denote lipid accumulation within hepatocytes. "To clarify the role of PLD1 in autophagy and hepatic steatosis, we expressed PLD1 using adenoviral gene transfer." (PMID 27976696, 2016). "Thus, deciphering the specific function of lysosomal PLD1 is essential for the identification of new therapeutic strategies for hepatic steatosis." (PMID 27976696, 2016). "We used Pld1−/− mice to examine the role of PLD1 in hepatic steatosis." (PMID 27976696, 2016). "Thus, PLD1 plays an important role in hepatic steatosis via the regulation of autophagy." (PMID 27976696, 2016). "In summary, the results of this study demonstrate that a decrease in PA production by lysosomal PLD1 inhibits autolysosome formation in the Pld1−/− liver, leading to hepatic steatosis, without affecting insulin sensitivity." (PMID 27976696, 2016). "Taken together, our results demonstrate that hepatic steatosis in Pld1−/− mice is not coupled with insulin resistance." (PMID 27976696, 2016). "Thus, PLD1, but not PLD2, could be related to hepatic steatosis." (PMID 27976696, 2016).
Hypertension (2 papers, 2016 to 2020). The presence of chronic increased pressure in the systemic arterial system. "PLD1 modulates lipid signaling by catalyzing the hydrolysis of phosphatidylcholine into choline and the signaling molecule phosphatidic acid, which regulates multiple downstream pathways implicated in hypertension including cytoskeletal organization and inflammation." (PMID 27779208, 2016). "We identified novel mRNA-microRNA pairs potentially involved in hypertension-related pathways and differently-expressed, including MCL1/miR-20a-5p, APOL3/miR-4763-5p, PLD1/miR-4717-3p, and PLD1/miR-4709-3p." (PMID 27779208, 2016).
injury (2 papers, 2020). Damage inflicted on the body as the direct or indirect result of an external force, with or without disruption of structural continuity. "Previous studies have shown that PLD1 promotes cell proliferation and inhibits apoptosis, indicating that PLD1 may be implicated in the pathogenesis of kidney injury induced by Cd." (PMID 32337269, 2020).
liver disease (2 papers, 2016 to 2025). "Silymarin/silybin regulates a significant number of these lipid metabolic genes, including iPLA2/PLA2G6, ATGL/PNPLA2, PLD1, LPIN2, and by trend PNPLA3 (which is a major genetic risk factor for MAFLD 131) and HSD17B13, counteracting the observed dysregulation in liver diseases." (PMID 39897559, 2025).
metastatic cancer (2 papers, 2014 to 2022). A carcinoma which has spread from the original site of growth to another anatomic site. "Small molecules that directly inhibit PLD1 or PLD2 represent novel approaches for the investigation of potential treatment of metastatic cancer and inflammatory diseases." (PMID 24103483, 2014). "Small molecules that either indirectly or directly inhibit PLD1 or PLD2 represent novel approaches for the investigation of potential treatment of metastatic cancer." (PMID 24103483, 2014).
myocardial ischemia (2 papers, 2018). A disorder of cardiac function caused by insufficient blood flow to the muscle tissue of the heart. "Consequently, infarct size was increased and cardiac function was impaired 28 days after myocardial ischemia in Pld1-/- mice indicating that PLD1 is crucial for TNF-α mediated inflammation and TGF-β mediated collagen scar formation." (PMID 30555342, 2018). "Consequently, infarct size and cardiac function was not altered in FIPI-treated mice as observed for PLD1 deficient mice that display enhanced infarct size and declined ejection fraction and fractional shortening following myocardial ischemia." (PMID 30555342, 2018). "The impact of PLD1 in inflammatory diseases was also shown in peritonitis and cancer Moreover, PLD plays a role in myocardial ischemia and reperfusion injury." (PMID 30555342, 2018). "PLD1 has been shown to be involved in TNF-α expression and release upon myocardial ischemia and reperfusion injury." (PMID 29968773, 2018). "Thus, the phenotype observed in PLD1 deficient mice is related to enzymatic and non-enzymatic properties of PLD1 after myocardial ischemia and reperfusion injury." (PMID 30555342, 2018).
non-small cell lung carcinoma (2 papers, 2012 to 2021). A group of at least three distinct histological types of lung cancer, including non-small cell squamous cell carcinoma, adenocarcinoma, and large cell carcinoma. "In order to explore the relationship between the PLD1 gene and risk of non-small cell lung cancer (NSCLC), single nucleotide polymorphisms (SNP) in the PLD1 exon region were surveyed in 211 NSCLC patients and 205 normal controls." (PMID 23675264, 2012). "Since both radiation and alkylating agents are important as adjuvant therapy for preventing recurrence and metastases in locally advanced non-small cell lung cancer, our results may provide new insights into improving clinical outcomes by targeting the novel ALDOA/PLD1 axis." (PMID 35127525, 2021).
osteosarcoma (2 papers, 2017 to 2023). A usually aggressive malignant bone-forming mesenchymal neoplasm, predominantly affecting adolescents and young adults. "Since PLD1, which was also associated with the malignant phenotype of osteosarcomas, was positively correlated with Sp1, further studies are required to determine the potential role of targeted inhibition of PLD1 without/or in combination with Sp1 as an candidate therapeutic target in clinics." (PMID 29088790, 2017). "To learn the biological significance of PLD1 in osteosarcomas, we initially investigated its expression using immunohistochemistry." (PMID 29088790, 2017). "In this study, we looked at the expression and biological significance of Sp1 and PLD1 in osteosarcomas." (PMID 29088790, 2017). "In this study, we examined the expression and prognostic significance of PLD1 - a critical enzyme involved in lipid metabolism - in osteosarcomas." (PMID 29088790, 2017). "Taken together, these data suggest that PLD1 was pro-tumoral in osteosarcomas, making it of great significance to reveal the mechanism whereby PLD1 facilitates osteosarcoma progression." (PMID 29088790, 2017). "Taken together, our study finds that PLD1 was elevated in osteosarcomas, and that its high expression was an independent prognostic factor for the disease, suggesting that PLD1 can serve as a pro-tumoral factor in osteosarcomas." (PMID 29088790, 2017). "We also revealed that PLD1 was positively correlated with Sp1- a factor that was also elevated in osteosarcomas." (PMID 29088790, 2017). "Since PLD1 was also pro-tumoral in various cancers, we postulated that these factors were tightly correlated in osteosarcomas and function synergistically in promoting osteosarcoma initiation and progression." (PMID 29088790, 2017). "In this study, We found that PLD1 and Specificity Protein 1 (Sp1) expression were elevated in 137 osteosarcoma specimens with immunohistochemical staining." (PMID 29088790, 2017). "Despite this, no studies have systematically examined the expression pattern and prognostic value of PLD1 in osteosarcomas." (PMID 29088790, 2017). "Considering the biological significance of PLD1 in osteosarcomas, and the fact that Sp1 could transcriptionally activate genes associating with malignant phenotypes, we postulated that the two factors were positively correlated." (PMID 29088790, 2017). "Since our study found a positive correlation between Sp1 and PLD1, we postulate here that transcription activation might also apply to the positive correlation between Sp1 and PLD1 in osteosarcomas." (PMID 29088790, 2017). "Furthermore, survival analyses showed that elevated PLD1 confers a poor prognosis on patients with osteosarcomas, acting as an independent prognostic factor." (PMID 29088790, 2017). "It has been reported that phospholipase D1 (PLD1) - a key enzyme involved in lipid metabolism - is important for the initiation and progression of various human solid cancers; however, its biological significance and regulation in human osteosarcomas remain elusive." (PMID 29088790, 2017). "Taken together, our data revealed that therapeutic inhibition of PLD1, either without or in combination with Sp1, could provide an alternative approach for the management of osteosarcoma." (PMID 29088790, 2017).
retinal degeneration (2 papers, 2018 to 2019). Degeneration of the retina. "In these experiments, PLD1 was able to completely suppress the light-dependent retinal degeneration phenotype of Drosophila PLD mutants." (PMID 31189747, 2019).
rheumatoid arthritis (2 papers, 2020 to 2025). A chronic, systemic autoimmune disorder characterized by inflammation in the synovial membranes and articular surfaces. "PLD1 regulated the expression of proinflammatory genes in rheumatoid arthritis synovial fibroblasts." (PMID 32670393, 2020).
scrapie (2 papers, 2018 to 2023). A fatal disease of the nervous system in sheep and goats, characterized by pruritus, debility, and locomotor incoordination. "PLD1 activation was also implicated in the mitochondrial dysfunction in the brains of scrapie-infected mice as well as in AD brains, thus increasing the importance of downregulating PLD1 levels as a potential therapy." (PMID 36834781, 2023). "The increased activity of phospholipase D1 (PLD1) has been observed in scrapie-infected brains." (PMID 30337853, 2018).
thrombosis (2 papers, 2018 to 2025). "Together, these findings identify PLD1 and PA as critical mediators of NET formation, offering new insight into the lipid signaling pathways that underlie NET-associated disorders such as venous thrombosis." (PMID 41194921, 2025).
thrombotic disease (2 papers, 2017 to 2025). The formation of a blood clot in the lumen of a vessel or heart chamber; causes include coagulation disorders and vascular endothelial injury. "Overall, these results indicate that PLD1 deficiency confers protection against DVT, supporting the possibility that inhibiting PLD1 could provide therapeutic benefit in NET-associated thrombotic disorders." (PMID 41194921, 2025).
acute pancreatitis (1 paper, 2013). An acute inflammatory process that leads to necrosis of the pancreatic parenchyma. "PLD1-driven processes in particular were observed to be critical in transmigration of macrophages exiting the vasculature during immune responses such as those seen in acute pancreatitis or irritant-induced skin vascularization." (PMID 23383154, 2013).
adenoma (1 paper, 2023). A neoplasm arising from the epithelium. "We found that Escherichia shigella was positively correlated with PLD1/2 in not only the type II CRC subgroup but also the type II adenoma subgroup." (PMID 37529669, 2023).
breast tumours (1 paper, 2007). "The other five PLD1-positive breast tumours showed positive expression for phospho-Akt; however, only two of these cases were positive for phospho-mTOR." (PMID 17726467, 2007). "We began by evaluating the expression profile of a breast tumour specimen that had high-PLD1 mRNA levels." (PMID 17726467, 2007). "This particular breast tumour represents a case in which PLD1 and phospho-Akt are inversely expressed, and the PLD1/mTOR/p70S6k pathway is active in the cancer cells." (PMID 17726467, 2007). "Phospholipase D1 was expressed in 27 of the 42 breast tumours." (PMID 17726467, 2007). "We also found that PLD1 and phospho-Akt are coexpressed in some breast tumours, a fact which could complicate the utility of rapamycin-based therapies, as patients expressing both proteins could differ in sensitivity to mTOR inhibitors." (PMID 17726467, 2007). "Phospholipase D1 protein was overexpressed in 10 of 42 (24%) breast tumours examined by IHC." (PMID 17726467, 2007). "We have found that PLD1 mRNA levels are significantly higher in basal-like tumours; therefore, we reasoned that PLD1 may be inversely expressed with phospho-Akt in breast tumours with basal-like features." (PMID 17726467, 2007). "We are the first to report that PLD1 is highly expressed in some phospho-Akt-negative clinical breast tumours." (PMID 17726467, 2007). "Phospholipase D1 mRNA levels were higher in breast tumours that expressed high-mRNA levels of basal CKs 5 and/or 17, but PLD1 mRNA levels were not significantly higher in ER-negative tumours." (PMID 17726467, 2007).
cardiac valvular defect (1 paper, 2024). "In 2017, it was first reported that the variants of PLD1 gene were associated with the cardiac valvular defect." (PMID 39553471, 2024).
congenital heart malformation (1 paper, 2023). A disease that has its basis in the disruption of heart development. "It has been shown thatrecessive variants in the PLD1 gene are associated with severeright-sided congenital heart malformations in two families." (PMID 37808210, 2023).
Crohn disease (1 paper, 2021). A gastrointestinal disorder characterized by chronic inflammation involving all layers of the intestinal wall, noncaseating granulomas affecting the intestinal wall and regional lymph nodes, and transmural fibrosis. "Some ICGs, such as BDH2, CYP4V2, OIT3, PLD1 and SLC25A23, were reported as differentially expressed in ileum tissue from Crohn’s disease vs. non-inflammatory bowel disease control." (PMID 34098982, 2021).
dementia (1 paper, 2019). Loss of intellectual abilities interfering with an individual's social and occupational functions. "The preclinical outcomes reported here provide a clear evidence for the therapeutic potential of PLD1 inhibition in preventing progression of cognitive deficits in AD and related dementia." (PMID 31797996, 2019).
Developmental cardiac valvular defect (1 paper, 2023). "All causative, candidate, and novel variants were found in genes associated with genetic syndromes, with the exception of PLD1, which is associated with CHD alone (Developmental cardiac valvular defect, MIM 212093)." (PMID 36999085, 2023).
head and neck cancer (1 paper, 2021). A primary or metastatic malignant neoplasm affecting the head and neck. "On the other hand, in head-and-neck cancers, curcumin reduced the expression of phospholipase D1 (PLD1), the enzyme that catalyzes the production of phosphatidic acid." (PMID 34744708, 2021).
lipid metabolism disorder (1 paper, 2022). "The protein–protein interaction was further analyzed, and the targets of PPAP2C, CHPT1, PPAP2B, PLD2 and PLD1 with higher degrees in the PPI network could be the key targets for preventing and treating the lipid metabolism disorder induced by CRE infection." (PMID 36295794, 2022).
Onset (1 paper, 2023). The age group in which disease manifestations appear. "Another important novelty that emerges from our study is the potential of PLD1 therapeutics in late-onset AD (LOAD)." (PMID 36834781, 2023).
ovarian tumor (1 paper, 2022). "We previously reported that both PLD1 and PLD2 are overexpressed in solid metastases and malignant effusions compared with the ovarian tumor in HGSC." (PMID 36362078, 2022).
pericardial effusion (1 paper, 2025). Fluid collection within the pericardial sac, usually due to inflammation. "The pathogenic genome rate of fetal pericardial effusion was 7.9% (11/140), including 3 cases of trisomy 21 syndrome, 2 cases of Turner syndrome, 2 cases of large fragment deletion, 3 cases of microdeletion, and 1 case of a single gene mutation (PLD1 gene mutation)." (PMID 41401185, 2025). "However, our study identifies a broader phenotypic spectrum in fetuses carrying PLD1 mutations, including pericardial effusion – a feature not previously linked to PLD1 dysfunction." (PMID 41401185, 2025).
pheochromocytoma (1 paper, 2020). "In rat pheochromocytoma cells, we demonstrated that short interfering RNA (siRNA)-based knockdown of Rac1 inhibits hormone secretion by preventing the secretagogue-induced activation of phospholipase D1 (PLD1)." (PMID 32664294, 2020).
polycystic liver disease (1 paper, 2024). "PRKCSH has various aliases including 80K-H, hepatocystin, PCLD (polycystic liver disease), PLD1 (phospholipase D1, phosphatidylcholine-specific), G19P1, advanced glycation end product receptor-2 (AGE-R2), and Protein kinase C substrate 60.1 kDa protein heavy chain." (PMID 38571496, 2024).
pyrexia (1 paper, 2010). "Our study shows that TNFα-induced pyrexia was inhibited when PLD1 was knocked down." (PMID 20463923, 2010).
Senile plaques (1 paper, 2016). Senile plaques are extracellular deposits of amyloid in the gray matter of the brain. "Previous works reported that these PCs are decreased in micro-extracted senile plaques from the post-mortem AD brain, and it could be linked to the roles of PLA2 and PLD1 in Aβ activation." (PMID 27891075, 2016).
squamous cell lung carcinoma (1 paper, 2025). A carcinoma arising from squamous bronchial epithelial cells. "However, conventional predictive methods, encompassing tumour pathology, tumour staging systems, and PLD-1 expression levels, have proven ineffective in accurately predicting the response to antitumour immunotherapy (Squamous cell lung cancer)." (PMID 41050056, 2025).
stenosis (1 paper, 2025). "Mutations in PLD1 are known to cause developmental heart valve defect type 1 (DHVD1), characterized by congenital valve malformations such as aortic/pulmonary stenosis and regurgitation." (PMID 41401185, 2025).
Stroke (1 paper, 2020). Sudden impairment of blood flow to a part of the brain due to occlusion or rupture of an artery to the brain. "These tests also revealed that the inhibition of either PLD1 or both PLD1 and PLD2 affords protective effects against neurological deficit after stroke." (PMID 32971863, 2020).
synovitis (1 paper, 2018). Inflammation of a synovial membrane. "Genes such as NRAS, SPHK2, FOS, CXCR4, PLD1, GNAI2, and PLA2G4F were strongly implicated in synovitis of OA." (PMID 29968759, 2018).
trisomy 21 syndrome (1 paper, 2025). "In this study, the pathogenic genome detection rate was 7.9% (11/140) and included three cases of trisomy 21 syndrome, two cases of Turner syndrome, two cases of large fragment deletion, three cases of microdeletion and microduplication, and one case of a single-gene mutation (PLD1 gene mutation)." (PMID 41401185, 2025).
tuberculosis (1 paper, 2017). A chronic, recurrent infection caused by the bacterium Mycobacterium tuberculosis. "In this study, we further investigated the intracellular regulatory network of T. gondii GRA7-induced ASC, PLD1, and PKCα signaling pathways to help identify novel therapeutic modalities for tuberculosis." (PMID 28125719, 2017). "Drawing on the observation that GRA7-I and -III associate with ASC and PLD1, respectively, and which contributes to antimicrobial defense against MTB in macrophages, we next evaluated the in vivo efficacy of rGRA7 and its binding mutants in a mouse model of established tuberculosis." (PMID 28125719, 2017). "Our findings demonstrate that GRA7-I and -III play fine-tuning roles in the activation of HDTs and innate immune machineries through direct binding with ASC or PLD1 and may provide a unique opportunity for urgently needed therapeutic interventions against tuberculosis." (PMID 28125719, 2017).